FOXF2 (forkhead box F2)
Diseases named in the same sentence as FOXF2 in open-access papers (continued):
Sharing a sentence is not in itself a finding about the gene and the disease.
Hearing impairment (1 paper, 2023). A decreased magnitude of the sensory perception of sound. "Thus far, no heterozygous FOXF2 variants with hearing impairment have been described in literature, and FOXF2 is not a predicted HI-gene (HI score: 29.63%, pLI score 0.85)." (PMID 36964621, 2023).
Hepatic steatosis (1 paper, 2025). Steatosis is a term used to denote lipid accumulation within hepatocytes. "FOXF2 has been shown to downregulate the expression of Insulin Receptor Substrate 1 (IRS1) in adipose tissue, thereby reducing glucose uptake, and HDAC9 has been implicated in adipocyte hypertrophy, IR, and hepatic steatosis." (PMID 40699860, 2025).
lip (1 paper, 2019). "FOXF2 (rs2814820; p-value 3.90 × 10− 6) and TAF1B (rs1003652; p-value 4.54 × 10− 6) are near a cleft lip and cleft lip and palate risk loci, respectively." (PMID 31533690, 2019).
lymph node metastasis (1 paper, 2018). "FOXF2 protein relative expression was significantly associated with age, lymph node metastasis, myometrial invasion, and TNM stage." (PMID 30249755, 2018). "The patients along with ≥50 years or lymph node metastasis or myometrial invasion or III–IV TNM stage had much lower FOXF2 protein relative expression than the other patients (P<0.05 or P<0.01)." (PMID 30249755, 2018).
Nystagmus (1 paper, 2016). Rhythmic, involuntary oscillations of one or both eyes related to abnormality in fixation, conjugate gaze, or vestibular mechanisms. "Thus hemizygous expression of FOXC1 and FOXF2 may explain the corneal abnormalities, iridogoniodysgenesis and nystagmus observed in the patient." (PMID 27103944, 2016).
prostate tumor (1 paper, 2022). "Collectively, we show that Cxcl5, but not Cxcl9/10 from the stromal cells, is the major downstream effector of stromal Foxf2 in suppressing prostate tumor growth." (PMID 36369237, 2022).
skin cancer (1 paper, 2016). "FREAC2 (FOXF2) targets are downregulated across the development sequence, and although it has not been specifically implicated in skin cancer, downregulation of its expression promotes epithelial–mesenchymal transition in basal breast cancer." (PMID 27574101, 2016).
tumor (34 papers, 2010 to 2025). "To dissect the molecular mechanisms underlying the stromal Foxf2-mediated tumor suppression, we compared gene expression profiles of the control and Foxf2-expressing WPMY-1 and mPrSC cells by RNA-Seq." (PMID 36369237, 2022). "We focus on the mechanisms and signal pathways of tumour development initiated by aberrant expression of FOXF2, and we summarize the diseases and signal pathways caused by aberrant expression of FOXF2 in embryogenesis." (PMID 32503970, 2020). "Mutated miRNA may promote tumor growth by reducing FOXF2 expression." (PMID 39001478, 2024). "It is known to target the tumor suppressors such as FOXF2 and regulators of epithelial-mesenchymal transition (EMT) in other cancers, likely involved in silencing gene suppressors in the LSCC." (PMID 41436994, 2025). "For example, FOXF2 suppressed tumour growth by inhibiting abnormal DNA replication and cell proliferation in non-TNBC cells, and induced carcinogenic effects by upregulating genes that promote epithelial-to-mesenchymal transition (EMT) in TNBC." (PMID 38604999, 2024). "Our study establishes Foxf2 as a stromal transcription factor modulating the tumor immune microenvironment and potentially explains why cancers are relatively rare and indolent in the TZ prostate." (PMID 36369237, 2022). "FOXF2, known as a tumor suppressor, is downregulated in the epithelial mesenchyme to destroy the differentiation effect." (PMID 35164166, 2022). "We reasoned that Foxf2 regulates stromal production of cytokines and chemokines, thereby altering the tumor immune microenvironment." (PMID 36369237, 2022). "ELISA showed higher expressions of Tnfα and Ifnγ in the tumor lysates of the Foxf2-expressing group, indicating an enhanced T-cell activity." (PMID 36369237, 2022). "Collectively, these results indicate that a higher stromal Foxf2 expression suppresses tumor growth by enhancing the CD8+ T-cell infiltration and activity." (PMID 36369237, 2022). "The expression of miR-205-5p (p < 0.0001) and UBE2C (p = 0.0093) were upregulated in tumor tissues, while the expressions of miR-140-3p (p = 0.0293), PTPRM (p < 0.0001), GPD1L (p = 0.0002), and FOXF2 (p < 0.0001) were downregulated in tumor tissues." (PMID 35712349, 2022). "Conversely, suppressing Foxf2 in mPrSC cells promoted the growth of cocultured RM-1 cells in vivo and induced an immunosuppressive tumor microenvironment." (PMID 36369237, 2022). "Generally, FOXF2 and EGFR are associated with proliferation and anti-apoptosis in cancer, showing that the FOXF2 gene plays a critical role in tumor suppression." (PMID 35164166, 2022). "Several studies have shown that FOXF2 is a potential tumor suppressor, and it can inhibit epithelial-mesenchymal transition (EMT) and metastasis in breast cancer." (PMID 34568422, 2021). "The results indicated that FOXF2 had quite lower expression abundance in tumor tissues and its expression varied in different types of tissues." (PMID 34568422, 2021). "By using the HPA, TCGA, and GTEx databases, we analyzed the expression level of FOXF2 in various human tumor tissues and normal tissues." (PMID 34568422, 2021). "FOXF2 is often used as a tumor suppressor in gastrointestinal and reproductive tumors, and decreased FOXF2 expression indicates cell growth and metastasis that promote cancer progression." (PMID 33717680, 2021). "FOXF2 is a critical tumour suppressor in gastric carcinogenesis that mediates upregulation of the E3 ligase IRF2BPL to drive ubiquitylation and degradation of β-catenin, which blunts Wnt signalling and suppresses carcinogenesis." (PMID 34645493, 2021). "FOXF2 mediates cancer progression, either as a tumor-promoter or a tumor-suppressor, by regulating EMT, cell cycles, and cell matrix production." (PMID 33717680, 2021). "Different FOXF2 functions and expression forms have warning effects during the tumor stage, prognosis, and treatment of cancer." (PMID 33717680, 2021).
tumor (continued). "FOXF2 can inhibit the EMT programme of tumour cells by repressing Twist1 transcription, thereby reducing the metastatic capacity of BLBC cells." (PMID 32503970, 2020). "This article highlights the differences in the role of FOXF2 in different tumours and demonstrates that multiple factors can regulate FOXF2 levels." (PMID 32503970, 2020). "MiR-301 can affect lymph node metastasis of tumour cells, downregulate the expression of FOXF2 and reduce the inhibition of FOXF2 on the expression of Wnt5a57." (PMID 32503970, 2020). "Tumor tissues and Hela cells FOXF2 expression were lower than that in adjacent tissues and hEEC (P<0.01)." (PMID 30249755, 2018). "Together, our findings identify high levels of Foxf2 as a marker for good prognosis in early noninvasive stages of tumor development, but with poor prognosis in malignant stages." (PMID 30285803, 2018). "Consistent with the negative regulation of FOXF2 on the transcription of TWIST1, TWIST1 mRNA levels inversely correlate with the FOXF2 mRNA levels in TNBC tumor (Spearman’s rho = −0.421, P = 0.013)." (PMID 25848863, 2015). "We investigated whether upregulation of stromal Cxcl9/10 also played a necessary role in the Foxf2-mediated tumor suppression." (PMID 36369237, 2022). "Therefore, our study establishes Foxf2 as a transcription factor in the stromal cells that modulates tumor immune microenvironment." (PMID 36369237, 2022). "To determine whether Cxcl5 is a major player downstream of Foxf2, we investigated whether suppressing Cxcl5 can attenuate or ablate stromal Foxf2-mediated tumor suppressive effect." (PMID 36369237, 2022). "Although Foxf2 is differentially expressed between the stromal cells at the mouse proximal and distal prostatic ducts, it is technically infeasible to evaluate the impact of this differential expression pattern on tumor initiation and progression." (PMID 36369237, 2022). "Stromal Foxf2 expression suppressed the growth of RM-1 tumor in C57BL/6 hosts as expected." (PMID 36369237, 2022). "A better elucidation of FOXF2’s regulatory mechanism and how it inhibits or maintains cancer by regulating gene transcription may make it an attractive target for future anti-tumor intervention." (PMID 33717680, 2021). "Second, the interaction between FOXF2 and the tumor microenvironment cannot be ignored." (PMID 33717680, 2021). "The different roles of FOXF2 in tumours may be due to differences in the tumour microenvironment, organ heterogeneity, or the complex functions of FOXF2 itself." (PMID 32503970, 2020). "Regulating the expression level of FOXF2 is an ideal treatment for tumours." (PMID 32503970, 2020). "This leads to different tumour treatment options based on FOXF2." (PMID 32503970, 2020). "However, FOXF2 can both promote and inhibit proliferation, invasion and metastasis in tumours, depending on the type or subtype of the tumour." (PMID 32503970, 2020). "We report a dual function of the transcription factor Foxf2, acting as a tumor suppressor by promoting apoptosis and by repressing survival, while exerting protumorigenic activity at later stages of tumor progression, such as a promigratory function by inducing the disruption of cell-cell adhesion." (PMID 30285803, 2018). "Foxf2 may function as a tumor suppressor in early cancer development by promoting apoptosis, hence showing a poor prognosis in LN– patients with low Foxf2 expression." (PMID 30285803, 2018). "At 3–6 weeks after transplantation, the subcutaneous tumor volume of pcDNA 3.1-FOXF2 group was markedly lower than that of Blank and Vector groups (P<0.05), illustrating that overexpression of FOXF2 could inhibit Hela cells growth in nude mice." (PMID 30249755, 2018). "Thus, our data suggest FoxF2's role as a tumor promoter, however further studies are required to clarify this aspect." (PMID 26967567, 2016). "The evidence given above indicates FOXF2 may act as a tumor suppressor in tumorigenesis and metastasis." (PMID 27487137, 2016).
tumor (continued). "So FOXF2 might be a tumor suppressor and work by maintaining the balance of ECM and inhibition of EMT." (PMID 27487137, 2016). "In cancer, FOXF2 has been considered as a potential tumor suppressor." (PMID 27487137, 2016). "Our results showed that low levels of FOXF2 mRNA reflect the aggressive status of the tumor." (PMID 23620774, 2013). "Stromal Foxf2 may also mediate tumor suppressive effects via other mechanisms." (PMID 36369237, 2022). "Therefore, disrupting EMT-TF activation using a transcription factor with a synergistic effect and FOXF2 may help prevent tumor metastasis." (PMID 33717680, 2021). "In addition, FOXF2 is considered a biomarker for the diagnosis or prognosis of various tumours." (PMID 32503970, 2020). "Therefore, regulating the level of FOXF2 is an ideal treatment for tumours." (PMID 32503970, 2020). "Therefore, regulating the expression level of FOXF2 is an ideal treatment for tumours." (PMID 32503970, 2020). "In addition, patients with low FOXF2 mRNA levels in tumor had a worse prognosis." (PMID 23620774, 2013). "First, lncRNA H19, which is upregulated by forkhead box F2 (FOXF2), can recruit the EZH2 protein to bind to the phosphate and tensin homolog deleted on chromosome ten (PTEN) tumor-suppressor gene." (PMID 33050646, 2020). "Our data identify the transcription factor Foxf2 as one of the important regulators of EMT, displaying a dual function in promoting tumor cell apoptosis as well as tumor cell migration." (PMID 30285803, 2018). "Protein expression of the three target genes (FOXF2, RECK, MTSS1) was significantly higher in stable low miR-182-5p expressing xenograft tumor tissues." (PMID 23383207, 2013). "FOXF2 and MMP26 were primarily related to tumour metastasis and invasion." (PMID 34645493, 2021). "Many studies have shown that FOXF2 plays an important role in tumours, but its role is not identical or even opposite in different tumours or different subtypes of the same tumour." (PMID 32503970, 2020). "In addition to the biological behaviour of tumour cells, members of the FOX family are also involved in the development of human organs, especially FOXD116, FOXC117, FOXI28 and FOXF2, as described later." (PMID 32503970, 2020). "According to the different types or subtypes of tumours, the roles of FOXF2 are not the same or even opposite." (PMID 32503970, 2020). "FOXF2 plays an important role in tumours, but its role is not identical or even opposite in different tumours or different subtypes of the same tumour." (PMID 32503970, 2020). "Methylation of both tumor suppressors, FOXD3 and FOXF2, could be responsible for their down-regulation, thus disturbing their interaction with other proteins." (PMID 30987631, 2019). "Interestingly, we have identified several transcription factors like TRPS1, NFAT5, FoxF2, ELF4, RLF etc. which haven’t previously been reported to be involved in PDAC but shown to induce EMT, angiogenesis or proliferation of tumours in other organs." (PMID 31795960, 2019). "However, the upregulated methylation levels of FOXC2, FOXF1, FOXF2, FOXM1, and FOXN3 indicated that an epigenetic mechanism was not the main reason for the elevated FOX expression in tumor tissues." (PMID 36622275, 2023). "Additionally, although we showed that stromal Foxf2 did not delay peripheral tolerance towards the SV40 T IV antigen, the tolerance towards other tumor antigens might be affected." (PMID 36369237, 2022).
cancer (21 papers, 2013 to 2025). A tumor composed of atypical neoplastic, often pleomorphic cells that invade other tissues. "A deficiency of FOXF2 can activate the VEGF-C/VEGFR3 signalling pathway in BLBC cells so that cancer cells have lymphangiogenic mimicry characteristics and enhanced lymphatic metastasis abilities." (PMID 32503970, 2020). "This suggests that FOXF2 may be associated with the metastatic capabilities of cancer cells." (PMID 23620774, 2013). "The transcription factor, FOXF2, plays an important role in tissue development, extracellular matrix synthesis, and epithelial-mesenchymal interactions, implying that it may be associated with the metastatic capabilities of cancer cells." (PMID 23620774, 2013). "Research has shown that the high expression of FOXF2 in BLBC can reduce cancer cell stemness, while the low expression of FOXF2 can promote cancer cell metastasis." (PMID 40003882, 2025). "We also discussed the possible reasons why FOXF2 performs the opposite function in the same types of cancer." (PMID 33717680, 2021). "Many studies have shown that FOXF2 was dysregulated in different types of cancers and can be regulated by aberrant DNA methylation." (PMID 34568422, 2021). "In the present study, by exploring public databases, we found that FOXF2 was expressed to varying degrees in a variety of normal and cancer tissues in the human body." (PMID 34568422, 2021). "The dysregulation of FOXF2 also plays an indispensable role in tumorigenesis and development of other types of cancer." (PMID 34568422, 2021). "Epigenetic modifications that regulate FOXF2 expression, including DNA methylation and histone acetylation, are also involved in the occurrence of cancer." (PMID 33717680, 2021). "This study not only extends the role of FOXF2 in cancer but also proposes that the deregulation of pleiotropic TFs controlling embryonic development and tissue differentiation can lead to complex biological processes in cancer, which may underlie refractory cancer metastasis." (PMID 31222004, 2019). "We found that the addition of CTSK to CM from FOXF2-depleted cancer cells restored the reductions in the number and size of TRAP+ osteoclasts." (PMID 31222004, 2019). "The cancer cells with altered FOXF2 expression were evaluated in vitro for chemotactic migration, heterogeneous cell–cell adhesion, and soft agar colony formation in the MC3T3E1 cell-mimic bone microenvironment and BEAS-2B cell-mimic lung microenvironment." (PMID 31222004, 2019). "Conversely, CTSK knockdown attenuated the number and size of TRAP+ osteoclasts induced by the CM from FOXF2-overexpressing cancer cells." (PMID 31222004, 2019). "The epithelial-to-osteomimicry transition regulated by FOXF2 confers a tendency on cancer cells to metastasize to bone which leads to osteolytic bone lesions." (PMID 31222004, 2019). "We observed that the ability of cancer cells to invade the bone matrix was positively regulated by FOXF2 expression." (PMID 31222004, 2019). "TRAP staining showed that the number and size of TRAP+ osteoclasts induced by the CM from FOXF2-overexpressing cancer cells were significantly increased compared with those induced by control cell CM." (PMID 31222004, 2019). "Bothdownregulation of anti-apoptotic targets as well as activation of proliferativemetabolism have been observed as mechanisms contributing to MAPKi-R.Downregulation of FOXF2 has been shown to promote cancer progression, EMT, andmetastatic invasion." (PMID 29615030, 2018). "More advanced tumors with high Foxf2 expression correlate with shorter metastasis-free survival, supporting a role of Foxf2 in cancer cell invasion and metastasis formation." (PMID 30285803, 2018). "There were also associations unique to each cancer type, including USF1 and SMAD1 for BRCA, FOXF2 for HNSC, and NFE2L2 and NR3C1 for UCEC." (PMID 28139702, 2017).